IGLJ7 (immunoglobulin lambda joining 7)
Synonyms: J7
Gene: Immunoglobulin joining (J) gene on chromosome 22 (22,921,390 to 22,921,435, forward strand). Ensembl gene ENSG00000211684.
Diseases named in the same sentence as IGLJ7 in open-access papers:
IGLJ7 is named in the same sentence as 2 diseases in open-access papers, as found by Europe PMC text mining. Sharing a sentence is not in itself a finding about the gene and the disease.
IGLJ7 shares sentences with these, for which no sentence is quoted: Burkitt lymphoma (1 paper); malignant lymphoma (1).